ADAMTS4 (ADAM metallopeptidase with thrombospondin type 1 motif 4)
Description:
Cleaves aggrecan, a cartilage proteoglycan, at the '392-Glu-|-Ala-393' site and may be involved in its turnover. Also cleaves COMP. May play an important role in the destruction of aggrecan in arthritic diseases. Could be a critical factor in the exacerbation of neurodegeneration in Alzheimer disease.
Synonyms: ADAMTS-4; KIAA0688; ADAMTS-2; ADMP-1
Tractability: Small molecule: a structure with a bound ligand is known; a high-quality ligand is known; it belongs to a druggable protein family. Antibody: its Gene Ontology location is reachable by antibodies, with high confidence; UniProt places it where antibodies can reach, with medium confidence; UniProt predicts a signal peptide or a membrane-spanning region. PROTAC: a small molecule that binds it is known.
Target class: Metallo protease MAM clan; Metallo protease; Protease; Enzyme; Metallo protease M12B subfamily
Chemical probes: PICEATANNOL
Gene: Protein-coding gene on chromosome 1 (161,184,302 to 161,200,509, reverse strand). Ensembl gene ENSG00000158859.
Subcellular location: Secreted, extracellular space, extracellular matrix
Subcellular location (Human Protein Atlas): Nuclear speckles; Predicted to be secreted
Pathways (Reactome):
Disease: Defective B3GALTL causes PpS
Extracellular matrix organization: Degradation of the extracellular matrix
Metabolism of proteins: O-glycosylation of TSR domain-containing proteins
Gene Ontology:
Molecular function: metalloendopeptidase activity; metallopeptidase activity; peptidase activity; protease binding; protein binding; zinc ion binding
Biological process: proteoglycan catabolic process; extracellular matrix disassembly; extracellular matrix organization; proteolysis; skeletal system development
Cellular component: extracellular matrix; extracellular region; nuclear speck
Genetic constraint (gnomAD): Loss-of-function variants: 39 observed, 69.57 expected, observed/expected ratio (o/e) 0.56, 90% interval 0.43 to 0.73. The upper end of that interval is the gene's LOEUF score, 0.73, which puts it in group 2 of 6, group 1 being the genes least tolerant of losing a copy. Missense variants: 1,014 observed, 1,136.5 expected, observed/expected ratio (o/e) 0.89, 90% interval 0.85 to 0.94. Synonymous variants: 418 observed, 468.69 expected, observed/expected ratio (o/e) 0.89, 90% interval 0.82 to 0.97.
Homologues: Orthologues: chimpanzee ADAMTS4 (99% identical), macaque ADAMTS4 (99% identical), rabbit ADAMTS4 (94% identical), pig ADAMTS4 (93% identical), guinea pig ADAMTS4 (92% identical), dog ADAMTS4 (92% identical), mouse Adamts4 (90% identical), rat Adamts4 (90% identical), tropical clawed frog adamts4 (63% identical). Paralogues in human: ADAMTS1 (47% identical), ADAMTS15 (45% identical), ADAMTS8 (42% identical), ADAMTS9 (38% identical), ADAMTS5 (37% identical), ADAMTS20 (36% identical), ADAMTS6 (32% identical), ADAMTS7 (32% identical), ADAMTS10 (32% identical), ADAMTS12 (30% identical), ADAMTS18 (30% identical), ADAMTS17 (30% identical), and 13 more.
Diseases named in the same sentence as ADAMTS4 in open-access papers:
ADAMTS4 is named in the same sentence as 103 diseases in open-access papers, as found by Europe PMC text mining. Sharing a sentence is not in itself a finding about the gene and the disease. The quoted sentences say what the papers report.
osteoarthritis (57 papers, 2005 to 2025). A noninflammatory degenerative joint disease occurring chiefly in older persons, characterized by degeneration of the articular cartilage, hypertrophy of bone at the margins and changes in the synovial membrane. "The balance of ADAMTS4 and TIMP3 levels is crucial in the development of osteoarthritis, in which the overactivation of ADAMTS4 is implicated in its pathogenesis." (PMID 36721026, 2023). "ADAMTS4 is identified as aggrecanase-1, which is a major aggrecan-degrading enzyme and is implicated in the development of osteoarthritis." (PMID 36721026, 2023). "ADAMTS-4 and ADAMTS-5 are implicated in osteoarthritis development since ADAMTS-4/-5 double-knockout animals are less affected than wild-type mice." (PMID 20034386, 2009). "Genes associated with FAI and osteoarthritis include ADAMTS4." (PMID 41019141, 2025). "Such therapies are already being developed for the treatment of osteoarthritis, with inhibitors of ADAMTS4 and ADAMTS5 currently in phase III clinical trials." (PMID 41465277, 2025). "To explore the specific molecular mechanisms by which chronic circadian rhythm disruption causes osteoarthritis lesions in rat mandibular condylar cartilage, we examined the expression of matrix-degrading enzymes MMP13, ADAMTS4, and ADAMTS5." (PMID 39010104, 2024). "High concentrations of Mg2+ promote the synthesis of TIPM3 to further suppresses osteoarthritis by inhibiting the expression of ADAMTS4, ADAMTS5, and MMP-13." (PMID 36546928, 2022). "TIMP-3 has been proven beneficial in diseases such as rheumatoid arthritis, which is majorly driven by an excess activity of TIMP-3 target ADAM17, and osteoarthritis, which is characterized by cartilage breakdown due to ADAMTS-4 and -5." (PMID 36013323, 2022). "The latest research has shown that the SOX4 can participate in the pathological changes of osteoarthritis cartilage by regulating ADAMTS4 and ADAMTS5." (PMID 34006298, 2021). "A cyclic peptide derived from TIMP3 (61EASESLAG70 enclosed by a Cys at each end) targeting ADAMTS4 has been explored as a treatment for osteoarthritis, further investigation is required for its potential usage in patients." (PMID 32612540, 2020). "Pretreatment of human osteoarthritis chondrocytes for 2 h with IF (1, 10, and 50 μM) in medium culture reduced the expression of ADAMTS-4 and ADAMTS-5, induced by IL-1β." (PMID 32349420, 2020). "ADAMTS-4 and ADAMTS-5 are proteases with important developmental roles, associated with inflammatory disorders, in particular osteoarthritis, where cartilage degradation results in joint pain." (PMID 33063247, 2020). "We have recently demonstrated that Ucma inhibits ADAMTS4 and ADAMTS5 aggrecanase activity in vitro and that Ucma-deficient mice develop a more severe cartilage damage in experimental osteoarthritis." (PMID 29720262, 2018). "Recently, synovial fibroblasts have been reported to provide the higher levels of ADAMTS-4 in osteoarthritis." (PMID 29137610, 2017). "Specific proteases, including the aggrecanases ADAMTS‐4 and matrix metalloproteinase 3, are important in initiating and promoting cartilage degradation in osteoarthritis." (PMID 26124002, 2016). "In the context of osteoarthritis, both the collagenase MMP-13 and the aggrecanases ADAMTS-4 and ADAMTS-5 are susceptible to such ECM-mediated increase in TIMP-3 potency." (PMID 27582494, 2016). "The specific degradation of type II collagen and aggrecan by matrix metalloproteinase (MMP)-9, -13 and ADAMTS-4 and -5 (aggrecanase-1 and -2) in the cartilage matrix is a critical step in pathology of osteoarthritis (OA)." (PMID 25909781, 2015). "Increased expression of aggrecanase-1 (ADAMTS-4) has emerged as an important factor in osteoarthritis (OA) and other joint diseases." (PMID 23406982, 2013).
osteoarthritis (continued). "ADAMTS4-mediated aggrecan degradation in articular cartilage is widely recognized as a primary etiological factor in the pathogenesis of osteoarthritis, while its cleavage of both aggrecan and versican plays a crucial role in the instability of atherosclerotic plaques." (PMID 40002887, 2025). "ADAMTS4 is also involved in the pathogenesis of osteoarthritis." (PMID 41019141, 2025). "The genes enriched in the osteoarthritis pathway revealed by IPA of the DEGs in the palovarotene-treated chondrocytes included various matrix catabolic genes (Adamts4, Adamts5, Mmp9, Mmp10, Mmp12, and Mmp13) and cell death-related genes (Casp1, Casp3, and Casp6)." (PMID 39062860, 2024). "Additionally, miR-92a-3p downregulated the expression of ADAMTS-4/5 induced by IL-1β in chondrogenic hMSCs and human chondrocytes, thereby inhibiting the progression of osteoarthritis." (PMID 38816719, 2024). "Thanks to its broader inhibitory profile, TIMP-3 has been proven beneficial in diseases such as rheumatoid arthritis, which is majorly driven by an excess activity of TIMP-3 target ADAM17, and osteoarthritis, which is characterized by cartilage breakdown due to ADAMTS-4 and -5." (PMID 36013323, 2022). "What is more, the expression of ADAMTS4 genes in the culture of synoviocytes from synovial tissues obtained from patients with osteoarthritis was significantly inhibited by ETA, and much more strongly inhibited when the TNF-α inhibitor was combined with a neutralizing anti-IL-1β antibody." (PMID 35407621, 2022). "The cleaving process mediated by ADAMTS-4 and ADAMTS-5 releases the chondroitin sulfate–modified C-terminus from the chondrocytes into the synovium, and inhibitors could prevent osteoarthritis cartilage loss." (PMID 33063247, 2020). "HIF-2α downstream degradation factors, such as MMP-3,13 and ADAMTs-4,5, played essential roles in the degradation of cartilage aggrecan and had been recognized as one of the most primary targets for therapeutic intervention in osteoarthritis." (PMID 32083119, 2019). "ADAMTS4 expression and activation is increased in osteoarthritis and rheumatoid arthritis." (PMID 30621194, 2019). "Similarly, upon testing a few catabolic genes implicated in osteoarthritis, we observed a significantly lower upregulation of MMP3 and ADAMTS4 in the hiChondrocytes and juvenile chondrocytes." (PMID 29096706, 2017). "ADAMTS4 is a zinc metalloproteinase that has been extensively studied in various ECM remodeling-related diseases, such as osteoarthritis, atherosclerosis, aortic aneurysms and dissections, and so on." (PMID 40002887, 2025). "Nevertheless, our data can be used to design small molecule inhibitors for other pharmaceutical targets, for example ADAMTS4 and ADAMTS5 in osteoarthritis, ADAMTS7 in atherosclerosis, or ADAMTS8 in pulmonary arterial hypertension, which spare ADAMTS9." (PMID 40449594, 2025). "Increased expression of β-CATENIN has been found to directly increase the expression of MMP13, ADAMTS4, and ADAMTS5, ultimately leading to the degradation of joint cartilage matrix and the occurrence of osteoarthritis lesions." (PMID 39010104, 2024). "Members of the ADAMTS (a disintegrin and metalloproteinase with thrombospondin motifs) family, mainly ADAMTS-4 and ADAMTS-5, are major aggrecan-degrading enzymes in osteoarthritis." (PMID 36362216, 2022). "In mice with osteoarthritis (OA), EMF inhibited the expression of inflammatory cytokines, including IL‐1β, ADAMTS4, and MMP13." (PMID 34774092, 2021). "By the way, the degradation of articular cartilage in osteoarthritis is thought to be the results of ADAMTS5 and likely also of ADAMTS4 activity, two enzymes thought to be involved in degradation of certain SLRPs, e.g., of fibromodulin as well." (PMID 33028365, 2020). "A disinterring and metalloproteinase with thrombospondin motifs 4 and 5 (ADAMTS-4 and ADAMTS-5) have shown a critical role in cartilage destruction, and their expression is increased in osteoarthritis patients." (PMID 32349420, 2020).
osteoarthritis (continued). "In vitro and in vivo studies demonstrated that CJM reduced the IL‐1β‐, IL‐6, IL‐17‐ and TNF‐α‐induced up‐regulation of MMP3, MMP13, ADAMTS4, ADAMTS5 and COX‐2 and blocked osteoarthritis development in a destabilization of the medial meniscus mouse model." (PMID 31148341, 2019). "Other families of the matrix degrading enzymes can destroy the cartilage specific proteoglycans, ADAMTS4 and ADAMTS5 are described as major aggrecanases of osteoarthritis." (PMID 30621194, 2019). "ADAMTS5 appears to be the primary aggrecanase, which is responsible for aggrecanolysis and cartilage degeneration in murine experimental osteoarthritis, while evidence rises for a contribution of both ADAMTS5 and ADAMTS4 in human cartilage degradation." (PMID 29720262, 2018). "GLP-1 RAs such as liraglutide, exenatide, lixisenatide, dulaglutide, and geniposide share common chondroprotective mechanisms in osteoarthritis, including suppression of NF-κB (reducing IL-6, TNF-α, and COX-2), inhibition of matrix-degrading enzymes (MMP-3/13, ADAMTS-4/5), and attenuation OS." (PMID 41158135, 2025). "Chronic circadian rhythm disruption could lead to osteoarthritis-like pathological changes in rat knees, with increased expression of MMP3, MMP13, and ADAMTS4 in knee cartilage and decreased expression of BMAL1." (PMID 39010104, 2024). "The aqueous extract from Codium fragile decreased nitrite production, protein expression of iNOS, matrix metalloproteinase-13, a disintegrin and metalloproteinase with thrombospondin motifs (ADAMTS)-4, and ADAMTS-5 against IL-1β-induced osteoarthritis with the regulation of the MAPK/NF-κB signal." (PMID 37760047, 2023). "In patients with severe osteoarthritis, dysregulation of OPN, MMP-9, and metalloproteinase with thrombospondin motifs 4 (ADAMTS-4) and a disintegrin was demonstrated to be important for the pathogenesis, suggesting that MMP-9 and thrombin are induced in osteoarthritis." (PMID 34440210, 2021). "In osteoarthritis cartilage, ADAMTS-5 is thought to have a more influential role than ADAMTS-4." (PMID 22394620, 2012). "However, the dual deletion of ADAMTS4 and ADAMTS5 provided significant protection against proteoglycan degradation ex vivo and decreased the severity of murine osteoarthritis in vivo." (PMID 19889209, 2009). "Although studies using transgenic mice suggest that in these murine models of degenerative joint disease, ADAMTS5 is the pathologically induced aggrecanase, our data suggest that ADAMTS4 is the aggrecanase induced by proinflammatory cytokines in the human OA synovium." (PMID 17177994, 2006). "Previous studies revealed that the most active aggrecanases in human joint illness are ADAMTS-4 and ADAMTS-5 (aggrecanase-1 and aggrecanase-2, respectively), after analyzing synovial fluid samples from a variety of human joint diseases, including osteoarthritis." (PMID 37259405, 2023). "For example, WISP-3 overexpression in normal cartilage (C-28/I2) cells dramatically reduces the expression of ADAMTS-4 and ADAMTS-5, and markedly elevates matrix metalloproteinase-1 (MMP-1) and MMP-10 expression, leading to the degradation of cartilage and the development of osteoarthritis." (PMID 34680447, 2021). "Finally, we review the current literature regarding the development of synthetic inhibitors directed toward the aggrecanases ADAMTS4 and ADAMTS5, a strategy that might directly inhibit cartilage destruction and restore joint function in both rheumatoid arthritis and osteoarthritis." (PMID 25606593, 2014).
Arthritis (21 papers, 2006 to 2024). Inflammation of a joint. "ADAMTS4 shows significant aggrecanase activity and is implicated in articular cartilage degradation and arthritis, and ADAMTS4 mRNA and protein have been found to be highly expressed in herniated lumbar intervertebral discs." (PMID 36584111, 2022). "A splice variant of ADAMTS4, which resulted in the removal of the spacer domain and the inclusion of a unique C-terminus, was detected in the synovium of arthritis patients." (PMID 34268335, 2021). "Additionally, in vitro cleavage by arthritis-associated ADAMTS-4 and -5 proteases occurs at the same site." (PMID 32576155, 2020). "In addition, transcripts for MMP1 and ADAMTS4 (encoding proteases which degrade extracellular matrix proteins of cartilage and are found in the synovial fluid of injured and arthritis knees) were increased in the synovium in this same post-operative period." (PMID 32107493, 2020). "Knocking out WTAP in chondrocytes decreased the m6A level and significantly decreased the mRNA (ADAMTS4, ADAMTS5, MMP13, IL-6, IL-8, iNOS) and protein levels of arthritis-related genes (ADAMTS4, ADAMTS5, MMP13) in the OA cell model." (PMID 38172596, 2024). "The cytokines are the major factors to stimulate the matrix metalloproteinases (MMPs) and aggrecanase (ADAMTS-4 and 5) production, leading to the progression of arthritis, a common arthritis due to damaging the articular cartilage membrane." (PMID 35877372, 2022). "Due to their prominence in arthritis, the regulation of ADAMTS4 and ADAMTS5 gene expression by pro-inflammatory cytokines has been studied to some extent." (PMID 34268335, 2021). "Among ADAMTS proteases involved in arthritis, α2M was shown to inhibit both ADAMTS4 and ADAMTS5 in a dose-dependent manner." (PMID 34268335, 2021). "Several clinical trials have been conducted to test the safety and efficacy of arthritis-modifying candidate drugs that reduced aggrecanase activity, i.e., inhibited ADAMTS4 and ADAMTS5 in preclinical studies." (PMID 34268335, 2021). "ADAMTS4 is one of metalloproteases to degrade chondroitin sulfate proteoglycans leading to destruction of cartilage during arthritis or spinal cord injury." (PMID 33731780, 2021). "Several experiments have demonstrated that neutralizing antibodies and other methods play a significant role in the models of arthritis in restraining ADAMTS-4 or ADAMTS-5." (PMID 28167976, 2017). "Additionally, MMP-17 mediates C-terminal processing of ADAMTS4, one of the aggrecanases that are thought to play a role in arthritis." (PMID 34255809, 2021). "This suggested the possibility that ECM-bound or cell surface-bound ADAMTS4 may be mobilized through autocatalysis, which now allows ADAMTS4 to reach its substrate aggrecan and contribute to its degradation in cartilage resulting in arthritis." (PMID 34268335, 2021). "On the other hand, ADAMTS proteases are also involved in the pathogenesis of acquired and congenital connective tissue disorders, most prominently in arthritis, where ADAMTS4 and ADAMTS5 degrade aggrecan and contribute to the erosion of articular cartilage and joint degeneration." (PMID 34268335, 2021). "Additionally, a positive feedback loop between FURIN and TGF‐β1 has been reported in synoviocytes, which upregulates “A disintegrin and metalloprotease with thrombospondin motif‐4” (ADAMTS‐4); this eventually leads to the destruction of arthritis." (PMID 32840921, 2020). "In particular, ADAMTS4 and 5 have emerged as therapeutic targets in arthritis." (PMID 26025392, 2015). "Since arthritis is a disease of the entire joint, ADAMTS4 and ADAMTS5 may have variable activity depending on their localization and which cytokines are present to stimulate their gene expression and activation profile." (PMID 25606593, 2014). "Although it has yet to be established which aggrecanase is predominant in human arthritis, ADAMTS4 inhibitors still may be beneficial, particularly if they inhibit ADAMTS5 concurrently." (PMID 25606593, 2014).